MMP9 (matrix metallopeptidase 9)
Diseases named in the same sentence as MMP9 in open-access papers (continued):
Sharing a sentence is not in itself a finding about the gene and the disease.
tumor (continued). "To explain the heterogeneity, we performed a subgroup analysis and found that high MMP-9 expression was also associated with advanced tumor stage only in tissue specimens and not serum (tissue RR = 0.69, 95% CI: 0.60-0.80, serum RR = 0.92, 95% CI: 0.75-1.14)." (PMID 26918342, 2016). "Hence, LGSOC patients showing an attenuated M2-skewed phenotype (CD163+) compared to HGSOC, also expressed significantly lower MMP-9 expression in tumor samples." (PMID 27462782, 2016). "There is strong clinical and experimental evidence of an association between elevated levels of matrix metalloproteinase MMP9 and cancer progression, metastasis and shortened patient survival, as it plays a key role in tumor cell migration by digesting the basement membrane and ECM components." (PMID 26745629, 2016). "There is evidence that the anti-tumor properties of PL are mediated by the inactivation of the Akt/NF-kB signaling pathway and by the inactivation of MMP-9 and VEGF, two proteins that are considered important for the processes of invasion, angiogenesis and metastases." (PMID 25980443, 2015). "Two members of the MMP family, MMP-2 and MMP-9, are necessary for tumor invasion and metastasis." (PMID 26512779, 2015). "MMP-2 and MMP-9 play an important role in tumor cell migration and invasion." (PMID 25927362, 2015). "Thus, our dichotomous distinction for tumor MMP-9 expression will reduce the impact of subjective judgment when determining tumor MMP-9 positivity." (PMID 25888323, 2015). "MMP-9 has been reported to facilitate tumor growth, invasion, and angiogenesis." (PMID 25888323, 2015). "Moreover, OCT4B upregulated the expression of MMP2 and MMP9, which are known to promote tumor invasion." (PMID 25816351, 2015). "In light of this, enhanced MMP-9 expression by macrophages upon exposure to ZOL-LIP may be beneficial in the tumour microenvironment." (PMID 25588705, 2015). "Platelet activation by tumor cells is followed by platelet aggregation during which the invasive phenotype of tumors is enhanced by increasing the expression of matrix metallopeptidase-9 (MMP-9) and transforming growth factor β (TGFβ)." (PMID 27429862, 2015). "MMP-9, which belongs to a family of zinc-dependent endopeptidases, is collectively capable of degrading essentially all of the components of the extracellular matrix (ECM), and is considered to be associated with invasion and migration of tumor cell." (PMID 26325180, 2015). "MMP-9 and its family members also promote angiogenesis, a critical process required for tumor cell survival, by degrading the vascular basement membrane interstitium and by releasing sequestered vascular endothelial growth factor (VEGF), a well know angiogenic molecule." (PMID 25830682, 2015). "Tumor-secreted TGFβ is usually sequestered to the extracellular matrix as an inactive complex and becomes activated through enzymes such as neutrophil-derived elastase and MMP9." (PMID 26648665, 2015). "We first examined whether coexpression of TSP50 and 65 as well as TSP50 and MMP9 were correlated with tumor size and pathologic grade." (PMID 25811800, 2015). "Following serum-differentiation, upregulation of MMP9 was detected in GBM cells and elevated expression of MMP9 was also noticed in the invading tumor cells originating from the serum-differentiated cells in comparison to the tumors that originated from the undifferentiated cells." (PMID 26700636, 2015). "However, the prognostic impact of IHC detection of tumor MMP-9 expression in operable NSCLC is controversial." (PMID 25888323, 2015). "It was worth noting that the inhibitory effect of BTG1 on migration and invasion might be positively linked to MMP-9 hypoexpression because MMP-9 degrades various components of the extracellular matrix and enhances the tumor invasive and metastatic potentials." (PMID 26050197, 2015).
tumor (continued). "In addition, miR-33b antagomir attenuated the inhibitory effect of cordycepin on the expressions of MMP-2, MMP-9 and CD44 which are associated with tumor invasiveness at mRNA levels." (PMID 25868853, 2015). "We also found that BSN significantly inhibited tumor cell invasion activity in A549 cells, which may be explained by its ability to negatively regulate the expression of MMP-9 and COX-2 proteins." (PMID 25788267, 2015). "However, the clinical efficacy of tumor MMP-9 expression as a prognostic marker in patients with operable NSCLC remains controversial." (PMID 25888323, 2015). "However, in vivo prostate xenograft tumor RLN2 inhibited pro-MMP-9 expression, which was opposite to our study." (PMID 26229955, 2015). "Accordingly, MMP2 and MMP9 may function in primary tumor growth, invasion, and colonization, facilitating SK-sNEDD4 cell metastasis to the lung." (PMID 25823820, 2015). "MMP-2 (gelatinase A) and MMP-9 (gelatinase B), which degrades type IV collagen, the major structural component of basement membranes, are overexpressed in various malignant tumors and are known to play crucial roles in tumor migration and invasion." (PMID 25625511, 2015). "In addition, MMP-9 exerts diverse roles in the tumor dissemination process, such as tumor invasion, tumor-induced angiogenesis, and immunomodulation of the tumor microenvironment." (PMID 26656588, 2015). "MMP-9 is an independent predictor of tumor recurrence and survival in HCC patients." (PMID 25638165, 2015). "Another study used the median value of staining for tumor MMP-9 to define tumor MMP-9 positivity." (PMID 25888323, 2015). "Furthermore, tumor MMP-9 expression was an independent prognostic indicator of relapse in patients with adenocarcinoma (p = 0.035)." (PMID 25888323, 2015). "Additionally, neutrophil-derived HGF and MMP-9 facilitate tumor cell migration and invasion towards the newly formed vascular bed." (PMID 25734659, 2015). "Furthermore, GABA reversed the nicotine-mediated induction of proteins involved in tumor growth and metastasis including MMP9, MMP2, and EGR1." (PMID 26264026, 2015). "The MMP-9/NGAL status correlated well with MRI-based tumor assessments." (PMID 26663949, 2015). "Moreover, the role of p130Cas in regulating tumor cell invasion through the release of matrix metalloproteinases such as MMP-9 has also been reported." (PMID 26356564, 2015). "VEGF and MMP-9, the main mediators of tumor angiogenesis and invasion, could be induced by radiation-triggered NF-κB activity." (PMID 26539482, 2015). "Moreover, miR-206 also inhibited the expression of MMP-9, which was the key enzyme to promote tumor cell to invasion and migration." (PMID 26325180, 2015). "Moreover, the authors noted that the reduction in OGT expression in tumor cells was associated with decreased expression of MMP-2, MMP-9 and VEGF and blocked bone metastasis." (PMID 25315705, 2015). "MMP9 has been shown to have the most profound effects in mediating tumor angiogenesis." (PMID 26648665, 2015). "One type, MMP-9, has been assigned an important role during angiogenesis and tumor invasion." (PMID 25821815, 2015). "Because C3f, as a fragment of complement C3, exists throughout the blood circulation and within tumor tissues, it remains unclear whether other protease(s) among possibly hundreds in biofluids, in addition to MMP-9, could also specifically cleave C3f4." (PMID 25788424, 2015). "Therefore, we evaluated the expression of MMP-9 specifically, by gelatin zymography, in the tumor tissue lysate based on its enzymatic activity." (PMID 26135741, 2015). "Tumor MMP-9 expression was observed in 161 (38.6%) of 417 patients." (PMID 25888323, 2015). "Another important effect of MMP-9 that supports tumor growth is angiogenesis." (PMID 26819959, 2015).
tumor (continued). "Stimulation of tumor cells by PMA has been reported to lead to increased levels of MMP-9 secretion through activating several signaling pathways, raising the possibility that TSG101 depletion leads to increased levels of MMP-9 secretion through amplifying these signaling pathways." (PMID 26608825, 2015). "The positive expression rate of cell invasion marker MMP-9 was 86.76% (59/68) in tumor specimens." (PMID 25922553, 2015). "In this report, we demonstrated that antibody-mediated inhibition of MMP9 reduced primary tumor growth and metastatic lesions in an orthotopic xenograft model of CRC, and we were also able to interrogate the efficacy of targeting tumor-derived and stroma-derived MMP9 either singly or in combination." (PMID 25961845, 2015). "Our results not only pointed out that PMS significantly restricted allograft tumor growth at the concentrations chosen, but also demonstrate that the inhibition effect of PMS on MMP9/MMP2 activity may contribute to its anti-tumor effects." (PMID 26674531, 2015). "Additionally, our group has identified MMP9 as an important mediator of tumor metastasis to the liver and other groups have shown several additional MMPs to be important in metastasis." (PMID 25880591, 2015). "Some α3β1-mediated tumor cell functions may be due to its ability to induce the expression of matrix metalloproteinase-9 (MMP-9)." (PMID 25751421, 2015). "Treatment of mice with nifuroxazide inhibited the expression of MMP-9 in 4T1 tumor tissues." (PMID 25811798, 2015). "Thus, MMP-9 supplied by bone marrow-derived cells is responsible for enhancing tumor proliferation via both increased proliferation and reduced apoptosis of tumor cells." (PMID 26819959, 2015). "As MMP9 plays an important role in tumor invasion, the down-regulation of MMP9 may be involved in the inhibition of invasiveness by luteolin." (PMID 25638174, 2015). "Mechanistically, MMP-9, a key mediator of tumor cell invasion, might involve in the KLF4-mediated migration and invasion." (PMID 26517087, 2015). "The presence of tumor-associated macrophages (TAMs), especially in hypoxic region of tumor, seems indeed to facilitate the intravasation process, maybe via secretion of MMP-9." (PMID 26078762, 2015). "Furthermore, we observed that the expression levels of matrix metalloproteinase-9 (MMP9), a key molecule associated with the invasion potential of tumor cells, were decreased in Colo-357 shMUC4 and Capan-1 shMUC4 cells." (PMID 26393880, 2015). "Additionally, XH had a potent effect on reducing the expressions of MMP-2 and MMP-9 in LoVo cells and 4T1 (mouse breast cancer) tumor-bearing mice." (PMID 26170886, 2015). "Furthermore, this study indicates that MMP-9 is an important factors facilitating the spread of tumor cells through the lymphatic system." (PMID 26656588, 2015). "As a natural target of TIMPs, MMP-2 and MMP-9 play important roles in tumor invasiveness." (PMID 25883224, 2015). "The possible factors that may contribute in potential tumor invasion and metastasis are MMP-9, Bcl-2 and Cyclin D1 genes which are known to be regulated by AP-1." (PMID 26581505, 2015). "Therefore, it is reasonable to evaluate tumor MMP-9 expression with respect to relapse, which includes both recurrence and metastasis, rather than with respect to survival." (PMID 25888323, 2015). "Indeed, MMP-9 is an important regulator of tumor angiogenesis and invasion with a prominent role in the development of SCC and other carcinomas." (PMID 25751421, 2015). "Inhibiting the expression or blocking the function of MMP-9 to reduce tumor invasiveness may be an effective therapeutic strategy for the treatment and management of BCYW." (PMID 26656588, 2015). "The combined effect might explain the inverse correlation between sE-cadherin and MMP9 found in the present investigation, whereby reduced MMP9 and elevated sE-cadherin may drive tumor proliferation forward." (PMID 25967040, 2015).
tumor (continued). "VEGF and MMP-9 play an important role in tumor progression by promoting migration and invasion." (PMID 25405331, 2015). "Because elevated level of MMP-9 is well known to increase the migratory properties of tumor cells in vivo and in vitro, we next tested whether BMP-4 was able to suppress the invasion of HT1080 cells." (PMID 25897433, 2015). "As expected, MMP9 serves to break down the extracellular matrix to facilitate tumor invasion." (PMID 25823820, 2015). "Several studies have revealed that E-cadherin could down-regulate MMP-9 expression in human tumor cells." (PMID 26314959, 2015). "The differing species-specificity profiles of our preclinical antibodies provided us with a unique opportunity to compare the effects of inhibiting tumor-derived (human) and stromal-derived (mouse) MMP9 either singly or in combination in the HCT116 xenograft tumor model." (PMID 25961845, 2015). "Studies show that Mmp-9 is very important in tumor incidence and metastasis and may have an anticancer effect in colitis-associated colon cancer and pancreatic neuroendocrine tumor." (PMID 25352026, 2015). "Among the MMPs family, MMP-9 plays an important role in tumor invasion and metastasis." (PMID 26663949, 2015). "Western blotting data on MMP-9 revealed that placebo treated groups demonstrated the highest expression levels compared to other treatment groups in PC-3 tumour biopsies, and that ACA in combination with rhAFP was capable of inhibiting cellular migration and invasion." (PMID 26158863, 2015). "Gelatinase B/MMP-9 degrades Surfactant protein D (SP-D), an important component of innate immune defence, leading to loss of innate immune function, limiting SP-D involvement in tumour immunology and renders oncology patients more susceptible to infection." (PMID 24473089, 2014). "Hence, the MMP-9 present in tumor epithelial cells can represent a specific target for the diagnosis and treatment of metastatic CRC." (PMID 24737953, 2014). "In particular, MMP2 and MMP9 are key mediators of invasion, metastasis and tumor angiogenesis." (PMID 25238232, 2014). "One possible reason for this decreased level in patients might be the changes of MMP9 concentration with tumor progression." (PMID 25469360, 2014). "In addition, we have proposed three other genes, E-cadherin, Stat3, and MMP-9, as prognosis biomarkers of tumor metastasis." (PMID 24647137, 2014). "Suppression of MMP-2, MMP-9 and uPA activity and expression could be a valid strategy to prevent tumor metastasis and invasion." (PMID 25222667, 2014). "In addition, we found that in PMA-treated U937 cells, HSPB1 cleavage occurred depending on MMP9, suggesting that in tumor microenvironment, macrophages play a role in MMP9-induced HSPB1 cleavage." (PMID 24465581, 2014). "However, several large studies examining MMP9 expression in human tumors by immunohistochemistry have demonstrated that MMP9 is most widely produced by tumor cells, with lower incidence of expression in fibroblasts and immune cells." (PMID 24811362, 2014). "The discrepancies in MMP-9 expression could be partly explained by differences in the degree of invasiveness of the tumor samples used in the studies or by the sensitivity of detection methods." (PMID 24978435, 2014). "It is also worth mentioning that we could not find any statistically significant correlation between the expression of MMP-9 in the tumor stroma and the occurrence of metastasis or overall survival in the same patients." (PMID 25151367, 2014). "This may consequently inhibit the expression of target genes, such as MMP-9, preventing the progression of the cell cycle and subsequently leading to the suppressed tumor cell migration and invasion observed." (PMID 25009665, 2014). "Moreover, a significant finding of our study is the demonstration that downregulation of NPRA can suppress tumor invasion and migration and is associated with MMP2 and MMP9 expression." (PMID 24885858, 2014).
tumor (continued). "Among the MMPs, a subset called gelatinases, consisting of MMP-2 (gelatinase A) and MMP-9 (gelatinase B), has gained the most attention in studies on the acquisition of invasive and metastatic tumor properties, as they degrade collagen IV, the major component of the basement membrane." (PMID 24778099, 2014). "Therefore, this study yielded additional insight into the potential value of the biomarkers investigated here, particularly, the utility of MMP-2 and MMP-9 expression for predicting the invasive behavior of the tumor and justification for therapy." (PMID 25097794, 2014). "Basally, PC3 tumor xenografts are strongly positive for MMP-9, MMP-2, and uPA." (PMID 24900952, 2014). "This identifies an anti-angiogenic, tumour suppressing function for gelatinase B/MMP-9." (PMID 24473089, 2014). "Taken together, our results suggest that HSPB1 is mainly cleaved by MMP9 during tumor progression." (PMID 24465581, 2014). "One possibility is that tumor cell MMP9 may carry out specialized functions made possible by specific localization, through generation of high local concentrations at a key point of action." (PMID 24811362, 2014). "Moreover, the expression of MMP9, a marker of tumour-angiogenesis is significantly decreased in IL-23p19-/- mice." (PMID 25015728, 2014). "In this case, galectin-7 expression could be induced by nuclear factor-kappa B, a transcription factor and a positive regulator of MMP-9 known to be expressed in highly aggressive tumor cells." (PMID 24515895, 2014). "The antiangiogenic effects were substantially enhanced when the agents were combined, which may due to the reduced expression of matrix metallopeptidase-9 in tumor tissues (MMP-9)." (PMID 24939055, 2014). "Two representative members, MMP-2 and MMP-9, were reported highly expressed in invasive tumours." (PMID 24912879, 2014). "In other types of tumor cells, binding of MMP9 to specific integrins can promote cell migration." (PMID 24811362, 2014). "STAT3 activation might be involved in tumor progression by modulation of the expression of factors related with cancer such as MMP9." (PMID 25359779, 2014). "In addition, we analyzed MMP-9 activity in PTC tissues showing various degrees of tumor infiltration." (PMID 24778099, 2014). "Given our results supporting a role for tumor cell-produced MMP9 in the invasion and metastasis of cell lines derived from human basal-like triple negative breast tumors, we hypothesized that MMP9 may be particularly highly expressed in these types of cancers." (PMID 24811362, 2014). "The expression levels of tumor promoting M2 markers: Cox 2, uPA, MMP9, MMR, arginase and VEGF are significantly higher in Mθs sorted from LLC tumors of WT while Mθs sorted from Rac2-/- mice displayed higher levels of proinflammatory cytokines, which are considered as M1 markers; IL1 and TNFα." (PMID 24770346, 2014). "Enhanced tumor growth and metastasis has been also shown in Gulo−/− ascorbate-deficient mice compared to ascorbate-supplemented mice, and this was associated with increased HIF-1 target gene expression (MMP9 and VEGF)." (PMID 24551593, 2014). "Finally, we wanted to correlate clinical outcome characteristics such as onset of metastasis, survival rates and tumor relapse with MMP-9 levels." (PMID 25151367, 2014). "Additionally, VEGFR1 expression on highly metastatic 3LL-LLC tumor cells induces MMP9 expression in premetastatic lung endothelial cells and macrophages." (PMID 24827582, 2014). "MMP-2 and MMP-9 are responsible for extracellular matrix degradation, and for the consequent neo-angiogenesis, vascular invasion and metastatic potential that characterize malignant tumours." (PMID 25432084, 2014). "Interestingly, implantation of SEMA7A knockdown tumor cells decreased the production of MMP-9 by intraperitoneal macrophages in both unstimulated and LPS-stimulated cultures." (PMID 24550834, 2014).